EGFR (epidermal growth factor receptor)
Diseases named in the same sentence as EGFR in open-access papers (continued):
Sharing a sentence is not in itself a finding about the gene and the disease.
tumor (continued). "Furthermore, NLGN3 has been shown to phosphorylate key receptors on tumor cells, including VEGF, epidermal growth factor receptor (EGFR), fibroblast growth factor receptor (FGFR), and integrins, thus exerting their biological effects." (PMID 39469896, 2024). "The researchers also elucidated that erlotinib, an epidermal growth factor receptor (EGFR) tyrosine kinase inhibitor, exerts its antineoplastic effects by curtailing tumor angiogenesis and fortifying existing vasculature, thereby obstructing tumor vascular remodeling." (PMID 40353137, 2024). "These inhibitors can selectively suppress abnormal ERK signalling and feedback activation of EGFR driven by BRAF‐mutant dimers in tumour cells without affecting the function of RAF protein in normal cells." (PMID 39073010, 2024). "AC480, a novel EGFR and HER2 inhibitor, administered before and during exposure to gamma radiation, was discovered to enhance the radiosensitivity of HNSCC cells and significantly reduce tumor size in vivo." (PMID 39239273, 2024). "In addition, 60% of TNBC samples were classified as basal-like (based on CK5/6 and/or EGFR expression in >10% of tumor cells) and 36% had a molecular apocrine phenotype (based on positive staining for AR and FOXA1 in ≥1% of tumor cells)." (PMID 39723208, 2024). "Secondly, compared to EGFR, αVβ6 is not or only poorly expressed in normal tissue, thus improving the contrast between healthy and tumor tissues." (PMID 38951897, 2024). "Anti-tumor efficacy was not seen in NSCLC cells with mutations in those genes, indicating that EGFR and KRAS mutation status can be predictive markers of response to IGF-1R TKIs." (PMID 38540176, 2024). "EGFR inhibitor drugs show variable success in effectively penetrating the BBB to target the tumor without reaching toxic levels." (PMID 38396993, 2024). "Several retrospective analysis has shown that primary tumor sidedness (PTS) might play a decisive role in the sensitivity to anti-EGFR mAbs therapy, and limited benefit was reported in patients with RAS wild-type right-sided tumor." (PMID 38217945, 2024). "In a xenograft mouse model representative of EGFR-mutated NSCLC, individual administration of either anti-PD-L1 or anti-CD73 antibodies fails to curtail tumor growth, in stark contrast to the isotype control." (PMID 39015563, 2024). "In clinical practice, EGFR testing is not available for some patients since high-quality genetic testing of tumor tissue is challenging due to many factors." (PMID 38730287, 2024). "Given the upregulation of HER3 in resistance to EGFR- or HER2-targeted therapy, the use of HER3-targeted monotherapy or combination strategies has been suggested to overcome acquired resistance mechanisms and augment tumor inhibition." (PMID 39337530, 2024). "Additionally, in tumor tissues, GE11-modified nanoparticles demonstrated a superior targeted aggregation effect and a higher affinity with EGFR." (PMID 38592437, 2024). "Taken together, we have presented here that the engineered destabilized 3'UTR ERBB2-30 delivered by IO nanocages inhibited the drug-resistant EGFR T790M NSCLC with 50% complete tumor lysis, 60% inhibition of ERBB2 protein, 50% therapeutic inhibition of tumor, and 80% reduction of malignant cells." (PMID 38699639, 2024). "Targeted inhibitors directed against specific mutated or rearranged oncogenes, such as epidermal growth factor receptor (EGFR), anaplastic lymphoma kinase (ALK), and receptor tyrosine kinase ROS proto-oncogene 1(ROS1) among others, exhibit promising anti-tumor activity." (PMID 39055566, 2024). "Focal tissue sampling, however, fails to assess both the spatial and temporal tumor heterogeneity, while diverse prognosis to epidermal growth factor receptor (EGFR)-tyrosine kinase inhibitors (TKIs) highlights the necessity of EGFR genotype stratification." (PMID 38398222, 2024). "EGFR and PD-L1 were specifically expressed in human OSCC cell lines and tumor xenografts." (PMID 39183296, 2024).
tumor (continued). "For example, even though HER2 T-BsAbs were more effective in treating SW1990 tumors than EGFR T-BsAbs, pairing the HER2 Fab with the less effective EGFR Fab in the heterodimeric EGFRxHER2 BsAb did not significantly diminish the overall anti-tumor efficacy." (PMID 38650005, 2024). "We have previously shown that EGFR and MMP1 act as key players in PM motility and EMT (epithelial to mesenchymal transition)‐like changes, and EPHA5 and PARK2 have been described to both drive and inhibit tumor cell migration." (PMID 36550787, 2024). "Anticipating the development of such BsAbs, targeting both EGFR and ERBB2 signaling pathways could not only synergistically inhibit tumor growth and enhance anticancer efficacy, but also effectively prevent resistance caused by mutations in either target." (PMID 38713378, 2024). "In addition, we performed paired analysis of RNA sequencing and IHC data of patient-derived tumor xenograft (PDX) samples, and estimated that EGFR and MUC1 were expressed in 97.5% of LUAD samples of The Cancer Genome Atlas Program (TCGA) database." (PMID 39664199, 2024). "Furthermore, EGFR TKIs enhanced the induction of MHC class I and MHC class II molecules by IFN-γ, inhibiting immune evasion by tumor cells." (PMID 38898505, 2024). "This article reviews the dysregulation of the EGFR, PI3K/AKT/mTOR, Hippo, pyroptosis, and PD-1/PD-L1 signaling pathways in HBC and CMT, as well as the corresponding drugs used to inhibit tumor growth, with the aim of providing theoretical support for the development of more efficient drugs." (PMID 39796003, 2024). "The anti-tumor effects of representative receptor blockades, such as trastuzumab (Herceptin) and cetuximab (Erbitux), are primarily achieved by directly interacting with the tumor surface receptors HER-2 and EGFR, respectively." (PMID 39013849, 2024). "Tyrosine kinase inhibitors (TKIs) incorporate a broad range of small molecule therapeutics which may target oncogenes (e.g. Epidermal Growth Factor Receptor, EGFR) or other targets in the tumour microenvironment (e.g. Vascular Endothelial Growth Factor, VEGF)." (PMID 39077464, 2024). "Additionally, miR-411-5p accelerated the growth of lung tumors, significantly reduced the expression of SPRY4, and simultaneously activates EGFR, AKT signaling, and the epithelial-mesenchymal transition (EMT) in tumor tissues in vivo." (PMID 39343796, 2024). "GTVA and NTVA mice, transduced with EGFR* did not develop tumours, only further crossing into an Ink4a heterozygous or Ink4a null background increased the tumour incidence to nearly 50%." (PMID 39324445, 2024). "Recent data from our group and others indicate that tumor cell–intrinsic factors in PDAC, such as CXCL1, EPHA2, USP22, EGFR, and the prostaglandin synthesis enzyme COX-2, promote myeloid cell infiltration that negatively impacts T cell infiltration, function, and tumor rejection." (PMID 39298269, 2024). "The anti-EGFR AY13 mAb could represent a tool for the specific detection of EGFRhigh tumors, especially when combined with more tumor-specific antibodies in a simultaneous multicolor codetection approach, but this requires further investigation." (PMID 38883274, 2024). "In addition, EGFR activation is also related to aggressiveness in malignant CMC, including increased angiogenesis, large tumor sizes, tumor necrosis, higher mitotic rates, advanced clinical stages, and malignancy." (PMID 38338029, 2024). "Gefitinib suppressed tumor POMC expression and downstream EGFR tumor signaling." (PMID 38862897, 2024). "Each distinct tumour type or genotype might regulate the amount of aEGFR, tEGFR, and CD63 EV-carrying forms of such EGFR analytes." (PMID 38830977, 2024).
tumor (continued). "EGFR and PTEN could alter receptor tyrosine kinase (RTK)/PI3K/AKT/mTOR pathway and promote tumor progression." (PMID 39208202, 2024). "Both EGFR and MET receptors play crucial roles in tumorigenesis, driving the growth and spread of cancer by promoting oncogenic signaling and fostering a supportive tumor microenvironment." (PMID 38910714, 2024). "Roughly, EGFR and MUC1 were detected on the same tumor cells in 63 (98.4%) LUAD and 76 (91.6%) CRC samples, which included samples with at least 1% of tumor cells stained positive with both EGFR and MUC1 regardless of staining intensity." (PMID 39664199, 2024). "Moreover, targeting EGFR led to the accumulation of stem-like cells in ACC, which contributed to tumour development." (PMID 39258959, 2024). "Besides, in two in vitro patient-derived tumor models, we found that the combination effects of HLX02 and HLX22 are stronger in model with high EGFR expression compared with model with low EGFR expression." (PMID 38982548, 2024). "Radiation induces PD-L1 expression in tumor cells via various pathways like DNA damage/ATM/STAT3/IRF3 axis, IFN-γ/JAK/STAT/PD-L1 pathway, cGAS-STING signaling, epidermal growth factor receptor (EGFR)/PI3K-AKT cascade, and the HIF-1α signaling." (PMID 38771260, 2024). "In the pediatric GBM, among the three tumor subtypes classified by DNA methylation landscape (MYCN, RTK1, and RTK2), it was found that MYCN was enriched for MYCN amplification, RTK1 enriched for PDGFRA amplification, and RTK 2 enriched for EGFR amplification." (PMID 38474286, 2024). "In addition, the interaction of HA and CD44 enhances epidermal growth factor receptor (EGFR)-mediated pathways, which leads to tumor progression." (PMID 39091989, 2024). "The tumor stained positive for thyroid transcription factor 1 (TTF1), cytokeratin 7 (CK7), and Napsin A, but negative for CDX-2, cytokeratin 20, and anaplastic lymphoma kinase (ALK), and presented a wild-type epidermal growth factor receptor (EGFR)." (PMID 39594178, 2024). "In contrast to the increase in immune cells and cytokines within the NDV-infected tumor tissues, the levels of the vascular endothelial growth factor (VEGF-A) and vascular endothelial growth factor receptor (EGFR) were reduced, particularly in the rLaSota-BC-RFP group." (PMID 39458338, 2024). "Therefore, treatment selection mostly has to rely on results from other tumor entities, e.g. breast cancer for DNA damage repair alterations, cholangiocarcinoma and urothelial carcinoma for FGFR alterations, and NSCLC for EGFR alterations." (PMID 38899374, 2024). "While other EGFR-TKIs may exhibit distinct resistance profiles, gefitinib serves as a representative model to explore how FZYA impacts EGFR-TKI resistance and tumor subtype transdifferentiation." (PMID 39735556, 2024). "Moreover, functional experiments have validated that the overexpression of NT5DC2 can impede EGFR ubiquitination, leading to the promotion of HCC cell proliferation and cloning in vitro, as well as the stimulation of tumor growth in vivo." (PMID 37405532, 2024). "The 10 mg/kg dose of P6-SN38 in a side-by-side EGFR+/EGFR− xenograft shows eradication of the EGFR+ tumor with good tolerance, but no inhibition of tumor growth of the EGFR− counterpart." (PMID 39771591, 2024). "In this regard, populations of microglia, monocyte/macrophages, oligodendrocytes with their precursors (OPCs), pericytes and endothelial cells were readily distinguished and comparable, but not identical between tumours with intact or disrupted EGFR gene." (PMID 38570528, 2024). "Herein, we sought to evaluate the rare cases with an EGFR/CEP7 ratio of <2 but a copy number of ≥5 for both EGFR and CEP7 and determine whether a cutoff ratio of ≥2 would correctly classify these tumors according to tumor biology." (PMID 38605523, 2024).
tumor (continued). "There are data suggesting that resistant mutations detected at very low variant allele frequency (VAF) represent small subclones of the total tumor burden and do not predict lack of response to anti-EGFR treatment." (PMID 39064004, 2024). "Moreover, Blocking EGFR activity in mice attenuated POMC expression, inhibited corticotroph tumor cell proliferation, and induced apoptosis." (PMID 38862897, 2024). "EGFR amplification is typical of highly aggressive primary GBM; about 50% of these tumours present a truncated and constitutively active form of EGFR (EGFRvIII), lacking part of the extracellular domain as a result of exons 2–7 deletion." (PMID 39595195, 2024). "CD109 induces EGFR-mediated STAT3 phosphorylation, which supports SCC cell migration, proliferation, and the cancer stem cell phenotype, highlighting its role in enhancing tumor aggressiveness and inflammation." (PMID 39990858, 2024). "In four of forty patients, EGFR was reported as amplified in the primary tumour, and non-amplified at recurrence." (PMID 36765632, 2023). "Immunohistochemical analysis of the prognostic value of CK5, CD117, and EGFR showed a longer DFS and OS periods for TNBC patients (with the tumor expressing at least one positive biomarker CK5, CD117 and/or EGFR) in contrast to the findings reported in other studies." (PMID 36766486, 2023). "While TMB and tumor purity did not significantly differ between the two stages, EGFR-mutant tumors had a significantly lower TMB than EGFR wild-type (WT) tumors, reflecting previous reports." (PMID 35881197, 2023). "EGFR regulates EMT-related proteins via AKT and influences tumor cell function." (PMID 37760803, 2023). "However, treatment against mixed tumors consisting of EGFR and EGFRvIII double-positive and EGFR-positive EGFRvIII-negative GBM cells yielded less survival benefit and tumor growth inhibition." (PMID 36768432, 2023). "SUVmax was not the only parameter used to predict EGFR mutations in NSCLC, but metabolic tumor volume (MTV) was also included." (PMID 37014455, 2023). "Under the strong selection pressure of EGFR-TKI, tumor cells undergo clonal selection." (PMID 37041601, 2023). "Transcriptomic profile of the patient’s tumor was retained in PDX (Pearson r = 0.88) and in xenoline (Pearson r = 0.63) as well as preservation of enriched signaling pathways (FDR Adjusted P < 0.05) including MAPK, EGFR and PI3K/AKT pathways." (PMID 37280243, 2023). "Change in tumor size rather than ΔKi67 was the preferred surrogate marker in a placebo-controlled window study of EGFR, Src, or combined blockade in operable HNSCC by Bauman and colleagues." (PMID 37575280, 2023). "We demonstrated that the cancer-specific EGFR targeted immunotoxin, hDT806, was able to act as a stimulator of the tumor-intrinsic innate immune response by activating the STING-IFN-I axis in both HNSCC cells as well as xenograft tumor models." (PMID 37898690, 2023). "Thus, GFP-Bro40 potentiates the degradation of EGFR mutant to block its downstream signaling in EGFR TKI-resistant NSCLC, thereby achieving potent anti-tumor and anti-metastasis effects." (PMID 37821451, 2023). "Moreover, the tumor growth was significantly inhibited with a tumor growth inhibition rate of 86.7% and the expression level of YAP, AXL, EGFR, AKT, and ERK in the tumor tissue was decreased by Polymer@Gef-YAP-siRNA with laser." (PMID 37415158, 2023). "In the previous anti-tumor targeted therapy, 83.6% and 76.0% of the patients in the fruquintinib group and regorafenib group received anti-VEGF therapy, and 25.5% and 20.0% of the patients received anti-EGFR therapy." (PMID 36937443, 2023).
tumor (continued). "In another study, VHHs interacted with EGFR tyrosine kinase residues in the vicinity of their catalytic area (the part to which the natural ligand binds) by using CDR3 and thereby hindered the function of EGFR, impeding tumor cell proliferation and migration." (PMID 37746282, 2023). "The study was performed by small peptides with phosphorylation sites (AEYLR, EYINQ, and PDYQQD), which were labeled with fluorescein isothiocyanate (FITC), in tumor cells of NSCLC with or without EGFR expression." (PMID 37744063, 2023). "In contrast to the resistance of the tumor organoids to chemotherapy drugs, multiple targeted agents showed good to exceptional activity, including the BTK inhibitor, ibrutinib (SPM score 97.3) and the EGFR inhibitor, afatinib (SPM score 95.9)." (PMID 37202426, 2023). "Consequently, we suggest that AR can modulate the immune system by acting on the core targets EGFR, MAPK1 and KRAS, thus improving the tumor immune microenvironment." (PMID 37065830, 2023). "In addition to targeting EGFR, the inhibition of its downstream effectors, such as PI3K, AKT, and/or mTOR, exerted similar tumor-suppressing effects on HCC cells." (PMID 37631344, 2023). "In addition, previous studies have demonstrated that epidermal growth factor receptor (EGFR) is closely related to the malignant transformation of squamous cells and the proliferation of tumor cells." (PMID 37152052, 2023). "Of the fourteen tumours that switched molecular subtypes between the primary and recurrent settings, six were initially EGFR-amplified, and eight were initially EGFR non-amplified." (PMID 36765632, 2023). "EGFR activation can increase dimer PKM2 expression and induce translocation of dimer PKM2 into the nucleus, where PKM2 acts both as a protein kinase and a transcriptional coactivator for HIF-1α in tumor tissues." (PMID 36874012, 2023). "Neratinib and erlotinib, both targeting the EGF receptor, were also active (SPM score 87.1 and 89.8, respectively) suggesting this patient’s tumor may be dependent on BTK and/or EGFR signaling." (PMID 37202426, 2023). "One of the limitations of this study is that we have not evaluated the effect of BUB1 ablation on EGFR signaling in mouse tumor models." (PMID 37399454, 2023). "Epidermal growth factor receptor (EGFR) inhibitors, (such as Cetuximab, Panitumumab, Erlotinib, and Gefitinib), work by focusing on and obstructing the signaling pathway and signal transduction that promote tumor growth." (PMID 37347077, 2023). "From these data we conclude that the MIL models learned to give high attention to tumor regions but likely boosted performance by also giving high attention to additional patterns that aid in classification such as immune infiltrates in EGFR negative samples." (PMID 36927889, 2023). "EGFR mutant NSCLC has a suppressed tumor microenvironment with few NK cells and CD8 T cells, but increased dendritic cell populations, and other immune cell populations remain similar to those seen in EGFR wild type tumors." (PMID 37033953, 2023). "As a result, non-physiological EGFR activation can result in unregulated cell division and, eventually, a growing tumor mass." (PMID 36768973, 2023). "Moreover, M2-like TAM activated BC cells via the EGFR/PI3K/AKT signaling pathway and upregulated sodium/glucose cotransporter 1 (SGLT1), leading to tamoxifen resistance and tumor growth." (PMID 37520246, 2023). "To further investigate whether NANOG expression in tumor cells is responsible for the acquisition of cisplatin resistance by autophagy-mediated EGFR activation, we silenced the NANOG gene in cisplatin-resistant tumor cells using siRNAs." (PMID 37165076, 2023). "Treatment with P6, a JAK inhibitor, represses tumor proliferation and pSTAT3 phosphorylation in EGFR-mutant cells (11–18, H1650, and H1975) but not in KRAS-mutant cells (H460)." (PMID 37381723, 2023).